FAP (fibroblast activation protein alpha)
Diseases named in the same sentence as FAP in open-access papers (continued):
Sharing a sentence is not in itself a finding about the gene and the disease.
cancer (continued). "As such, using a recently introduced FAP-targeted PET agent initially developed for patients affected with oncological diseases, we investigated a large cancer cohort imaged with [68 Ga]Ga-FAPI-04 to perform an in-depth analysis of plaque burden with radiotracer accumulation in the arterial tree." (PMID 37147478, 2023). "Firstly, by examining the expression levels of the COL10A1/FAP/FN1, we can sensitively detect whether COVID-19 infection is promoting cancer progression." (PMID 38063927, 2023). "Though increasing evidence has demonstrated the importance of FAP in cancer progression, no multifactorial analysis has been developed to investigate its function in gastrointestinal cancers until now." (PMID 37325617, 2023). "While the first outcomes of prospective trials of FAP TRT are still awaited, preclinical studies and selected case series showed encouraging data that FAP TRT may become a treatment option for different cancer types." (PMID 36813980, 2023). "Targeting FAP in human cancer patients with the humanized monoclonal antibody sibrotuzumab, which shows high affinity for binding to FAP, or the FAP enzyme inhibitor talabostat, which has not demonstrated clinical efficacy in NSCLC patients." (PMID 36672284, 2023). "FAP immunohistochemistry score was positively correlated with 68Ga-FAPI-46 SUVmax (r = 0.781 [95% CI, 0.376–0.936], p < 0.001) and SUVmean (r = 0.783 [95% CI, 0.379–0.936], p < 0.001) in cancer tissues." (PMID 36675506, 2023). "Attempts have also been made with the anti-FAP monoclonal antibody sibrotuzumab, but this strategy has not yielded satisfactory results in human cancers, including HNSCCs." (PMID 36980527, 2023). "For example, pCAFs (Cancer-promoting CAFs) inhibit antitumor immunity mainly by expressing FAP-α or a-SMA multiplex, while rCAFs (Cancer-restraining CAFs) inhibit pancreatic cancer growth with Meflin (glycosylphosphatidylinositol-anchored protein) as a biomarker." (PMID 37007004, 2023). "Moreover, some reports conclude that FAP is also expressed in cells during the EMT and carcinoma cells." (PMID 37168385, 2023). "It remains to be established whether compounds that, in addition to DPP-IV, inhibit other DPP-IV-like proteases, such as FAP, DPP8, and DPP9, may offer advantages over the use of more selective DPP-IV inhibitors in patients with cancer." (PMID 35565202, 2022). "Additionally, numerous ATC cancer cells expressed both CREB3L1 and the fibroblast marker FAP, indicating ATC cells possessed a CAF-like phenotype." (PMID 36192735, 2022). "We also investigated correlations between FAP and immunogenic cell death (ICD) in 33 cancers." (PMID 35359436, 2022). "CAFs express fibroblast activation protein-alpha (FAPα), smooth muscle actin alpha (α-SMA), PDGF receptor alpha (PDGFRα), PDGF receptor beta (PDGFRβ), and/or fibroblast specific protein 1 (FSP-1/S100A4), depending on the type of cancer." (PMID 35986369, 2022). "IMPLICATIONS FOR PATIENT CARE: FAPi PET uptake correlates strongly with FAP expression in cancer patients, and FAPi PET may thus serve as a predictive biomarker for FAP-targeted therapeutic approaches." (PMID 34740953, 2022). "We hypothesized that the expression profiles of CXCL12, CXCR4, and FAPα could provide valuable information regarding cancer invasion in LARC and cancer cell survival related to nCRT resistance in LARC." (PMID 34976180, 2022). "Our results suggest that dual-targeted therapy against cancer cells and CAFs may be more effective than single-targeted therapy for patients with high expression of both EGFR and FAP." (PMID 36418422, 2022). "The cancer-derived Transforming Growth Factor-β (TGF-β) in PDAC patients plays an important role in converting normal fibroblasts into myofibroblastic CAFs, which produce αSMA, and fibroblast activation protein (FAP)." (PMID 36685537, 2022). "Currently, several clinical trials targeting FAP, especially RO6874281, are ongoing across cancers." (PMID 36263225, 2022).
cancer (continued). "Because of its very recent advent in cancer diagnostics, FAP is not yet routinely used to identify cancerous tissue alterations in PC biopsies." (PMID 34854061, 2022). "In this translational study, we aimed to establish the spectrum of FAP expression across various cancers by immunohistochemistry and to explore whether 68Ga-FAPi-46 PET biodistribution faithfully reflects FAP expression in cancer patients." (PMID 34740953, 2022). "Absent in normal healthy adult tissue, FAP is normally expressed during development and highly upregulated at sites of active tissue remodeling, such as wound healing, fibrosis and cancer." (PMID 34854061, 2022). "Therefore, the development of heterodimers targeting dual FAP and PSMA receptors is considered a promising strategy for detecting malignant tumors." (PMID 35337180, 2022). "Given the high expression of FAP in cancer and the absence of significant uptake of FAP-targeting small molecule tracers in normal tissues, OncoFAP-based radioligands have inherent potential for theranostic applications." (PMID 36015106, 2022). "Conversely, the staining of FAPα and αSMA was absent in HSCs of normal liver tissue adjacent to carcinoma or in the angiogenic microvessels in the central area of CRCLM xenografts." (PMID 35951441, 2022). "Hence, FAP and CCL2 can be therapeutic targets because FAP develops cancer by activating CAF STAT3/CCL2 signaling." (PMID 34445235, 2021). "On the other hand, this “CAF targeted therapy” did not affect the cancer cells directly in vitro, as cancer cells did not express FAP." (PMID 33462372, 2021). "For example, FAP was shown to be highly expressed in CAFs rather than cancer cells and normal tissue in pancreatic cancer." (PMID 34852849, 2021). "However, many other enzymatic targets can be manipulated in this NRP-body construct, such as targeting FAP-expressing cells in PDAC since FAP has enzymatic activity and is overexpressed in both PDAC CAFs and cancer cells." (PMID 33499238, 2021). "A meta-analysis of 15 studies in solid tumours concluded that FAP is a negative prognostic factor in several human malignancies, especially when it is expressed in cancer cells." (PMID 34282761, 2021). "The levels of FAP and ENO1 in cancer tissues could predict the overall survival and recurrence-free survival in patients." (PMID 34035230, 2021). "During screening of the full-text articles, 18 articles were excluded as they only provided information on FAP-specific PET in cancer patients." (PMID 33606104, 2021). "While most studies therefore evaluate the application of FAP-specific PET in patients with various kinds of cancers, the use of FAP-specific PET in non-malignant indications has initially been limited to occasional case reports." (PMID 33606104, 2021). "For the promoters of the CXCL12 and FAP genes, the transcripts of whose were detected specifically in IVP-9TS fibroblasts, an extremely low and nonselective promoter activity was shown both in IVP-9TS and in cancer cell lines." (PMID 33804861, 2021). "On the other hand, FAP expression in cancer cells was much less frequent and most GBMs contained no or few FAP+ cancer cells." (PMID 34282761, 2021). "The fibroblast activation protein (FAP) has already been shown to be expressed at low levels in normal tissues but is highly expressed in the stroma of many cancer types." (PMID 34420105, 2021). "Elevated FAP expression and/or activity has been detected in multiple human cancers and serves as a negative prognostic marker for the overall survival time and progression of the disease." (PMID 33996747, 2021). "On the other hand, FAP-targeted NIR-PIT did not have any effect on cancer cells in a monoculture, showing specific efficacy for FAP-positive cells." (PMID 33462372, 2021). "In this study, we coupled the FAP-targeting specificity with the selective activity of Nav, an experimental drug with increased efficacy in CAFs and myofibroblast rather than in cancer cells." (PMID 33562504, 2021).
cancer (continued). "Furthermore, pathological analysis demonstrated that tissues from radiation-resistant carcinoma were infiltrated with substantial CAFs that stained positive for α-SMA and FAP when compared with radiosensitive NPC." (PMID 33648530, 2021). "Since the FAP-targeted NIR dye selectively accumulated in the stroma of all tested tumors, we believe that this agent has the potential to guide a surgeon in his/her effort to locate and resect all malignant lesions during a cancer surgery." (PMID 32483418, 2020). "Hence, we envisioned that simultaneous targeting of liposomes with FAP’scFv and HER2’scFv will potentially impact the HER2’scFv based rapid binding and deliver fluorescent cargos into cancer cells in vivo and enhance their fluorescence detection." (PMID 33076292, 2020). "CA-MSCs did not appear to be cancer-associated fibroblasts (CAFs) as demonstrated by the absence of upregulation of α-SMA, FAP, FSP1, or PDGFRα." (PMID 31504643, 2020). "Although a different FAP ligand linked to a PET imaging agent has already yielded excellent images of cancer patients in the clinic 46, no FAP-targeted 99mTc imaging agent has been reported to date." (PMID 32483418, 2020). "FAP has been the focus of many CAF-directed preclinical and clinical cancer studies." (PMID 31289350, 2019). "Using radiolabelled FAP-Inhibitors (FAPI) FAPI-02 and FAPI-04, the Haberkorn group demonstrated proof of concept for the clinical use of 68Ga-labeled FAPI PET/CT in various cancers with significant lower background uptake in the liver and brain compared to 18F-FDG." (PMID 30823564, 2019). "125I-FAPI-01 showed no significant binding to the FAP-negative cancer cell lines but targeted human and murine FAP-expressing cells with high affinity (half-maximal inhibitory concentration for human FAP, 39.4 nM)." (PMID 29626120, 2018). "As a result, the macrophages are coerced to instigate a wound healing response, identified by co-expression of FAP and HO-1, exemplifying Harold Dvorak’s seminal observation 40 years ago that cancers resemble ‘wounds that do not heal’18." (PMID 30054470, 2018). "This FAP knockout mouse develops and reproduces normally and shows no increase in the incidence of cancer, suggesting that FAP is not essential during development." (PMID 28158223, 2017). "Fibroblast activation protein α (FAP α) is not detectible in normal tissues, but is overexpressed by CAFs and is the predominant component of the stroma in most types of cancer." (PMID 26985769, 2016). "For example, FAP may form complexes with its homologous enzyme, dipeptidyl-peptidase (DPPIV), facilitating ECM degradation and thus promoting cancer cell invasion." (PMID 28033421, 2016). "FAP+ stromal fibroblasts are essential to maintain the TME and promote cancer progression." (PMID 26943036, 2016). "Fibroblast activation protein α (FAP α) is overexpressed by CAFs and is the predominant component of the stroma in most types of cancer, while it is not detectable in normal adult human tissues." (PMID 26985769, 2016). "Unlike the four markers which were detected in interstitial cells (such as α-SMA and vimentin) or the cancer cells membrane (such as CK-19), TGF-β and FAP expression was detected in the cytoplasm of cancer cells while twist was located in both cytoplasm and nucleus." (PMID 25189096, 2014). "Unlike the ubiquitous expression pattern of DPP4, FAP is expressed exclusively in fetal cells, stromal fibroblasts, wounded tissues, and the stromal fibroblasts of more than 90% of malignant epithelial tumors, but not in benign tumors or normal adult tissues." (PMID 24551161, 2014). "Nonetheless, while normal adult tissues are generally FAP-negative, its expression is detectable in the stroma of over 90% of carcinomas." (PMID 18447899, 2008). "Interestingly, first 211At‐labeled FAP‐targeting agents showed promise to treat cancers even though cancer cells are not directly targeted in this approach." (PMID 40888104, 2026).
cancer (continued). "Among fibroblasts, we identified cancer-associated fibroblast (CAF) phenotypes similar to CAF-S1 (40%), previously linked to immune suppression and Treg interaction in TNBC36, as well as a CAF-Other population (35%) which did not express FAP or SMA." (PMID 39975273, 2025). "As an additional means of testing ADC efficacy, we conducted cell killing assays using cellular reductive capacity as a readout for metabolic activity and cell viability, recapitulating the same dose-dependent and selective killing of FAP-expressing CWR-R1FAP but not CWR-R1 cancer cells." (PMID 39868181, 2025). "Also, we found co-expression of FAP and PDCD1 in 22 different cancer types (P < 0.05)." (PMID 39870619, 2025). "Unlike with FDG PET, where uptake is typically correlated with aggressiveness, FAP PET uptake may be due to many factors, including increased cancer cell migration, epithelial-mesenchymal transition, immunosuppression, promotion of angiogenesis, and chemotherapy/immunotherapy resistance." (PMID 39572227, 2025). "The lack of a clear relationship between FAP concentrations and survival in cancer patients in our study suggests that early post-radiation FAP measurements may not predict cancer outcomes or radiation response." (PMID 40690098, 2025). "However, FAP concentrations were not related to age in healthy volunteers (r2 = 0.04, P = 0.14) or cancer patients (r2 = 0.04, P = 0.45)." (PMID 40690098, 2025). "Anti-FAP recombinant antibody conjugated to a photoreactive dye, IR700, has been shown to discriminately eliminate FAP +ve CAFs in vitro in a dose-dependent manner − normal fibroblasts and OC cancer cells were unaffected with in vivo models having no observable side effects." (PMID 40379112, 2025). "FAP inhibitors (FAPis) have been exploited as small-molecule radioligands designed to specifically target FAP with high binding affinity and are actively being investigated for both positron emission tomography (PET) imaging and potential radioligand therapies across various cancer types." (PMID 39335703, 2024). "Additionally, FAP expression patterns in liver metastases of CRCs are consistent with those of the patient’s primary cancers, indicating the utility of FAP-targeting therapies in both metastatic and non-metastatic patients." (PMID 39335130, 2024). "Both FAP molecules themselves and FAP-positive cells in the TME may be involved in the proliferation, invasion, angiogenesis, and extracellular matrix (ECM) remodeling of cancer cells." (PMID 38475858, 2024). "FAP-targeted PET imaging, characterized by diagnostic sensitivity and specificity, has shown promise, with low uptake of FAP-targeted tracers in non-tumoral tissues and high uptake in a wide range of cancers, PDAC among them." (PMID 38540204, 2024). "FAP is highly expressed in a majority of cancers and is absent in over 90% of normal tissues." (PMID 39335130, 2024). "We unravel FAP+ CAF plasticity and crosstalk with both cancer and immune cells, and we identify 10 spatially-organized FAP+ CAF cluster-related cellular modules referred to as EcoCellTypes (ECT), which are composed of specific FAP+ CAF clusters and precisely localized within tumors." (PMID 38561380, 2024). "These agents, particularly FAP inhibitors (FAPIs), allow for non-invasive imaging that can complement existing modalities like [18F]FDG PET, offering high specificity and sensitivity in certain cancer types, revealing tumors that might otherwise go undetected." (PMID 39765634, 2024). "Moreover, specific DCN knockdown in breast fibroblasts modulated the expression/secretion of several CAF biomarkers and cancer-promoting proteins (α-SMA, FAP- α, SDF-1 and IL-6) and enhanced the invasion/proliferation abilities of these cells through activation of the STAT3/AUF1 signaling." (PMID 38667295, 2024).
cancer (continued). "Recent studies are utilizing this concept by using radiolabeled FAP inhibitors (FAPIs) as tracers for PET imaging and have shown the potential for the detection of both primary tumors and metastasis that were undetectable with 18F-FDG tracers for multiple types of cancers." (PMID 38540158, 2024). "The lack of correlation between CD31 and FAP expression in the stroma and cancer stage could be due to several reasons." (PMID 39022761, 2024). "By bioinformatic analysis, we found that FAP was positively correlated to the expression of M2 macrophages marker MRC1 across gastrointestinal cancers, suggesting that FAP may be involved in regulating M2 macrophages in these cancers." (PMID 37325617, 2023). "With the view to develop pan-cancer theranostic radiotracers, several research groups have shifted their scientific focus on imaging and/or treating various tumors by targeting not directly the cancer cells but FAP+ CAFs." (PMID 37284857, 2023). "According to a relevant study, the SUVmax, SUVmean and FAP immunohistochemistry scores of 68GA-FAPI-46 were higher in various cancer tissues than in adjacent non-cancer tissues: the SUVmax (7.7 vs. 1.6); the SUVmean (6.2 vs. 1.0); the FAP immunohistochemistry score (2.8 vs. 0.9)." (PMID 36675506, 2023). "In this study, we developed a FAP targeting ligand, LuFL, containing organosilicon-based fluoride acceptor (SiFA) and DOTAGA chelator, capable of labeling fluorine-18 and lutetium-177 in one molecular with simple and highly efficient labeling procedure, to achieve cancer theranostics." (PMID 36864362, 2023). "In addition to these well-studied and clinically relevant genes, novel target structures for theranostic approaches such as C-X-C Motif Chemokine Receptor 4 (CXCR4) and Fibroblast Activation Protein Alpha (FAP) emerged, with a growing spectrum of radioligand therapies in different cancer entities." (PMID 36672341, 2023). "Use of the radiolabeled FAP inhibitor (FAPi) [68Ga]-FAPi-46 PET has demonstrated heterogeneous localization of FAP in tumors in a clinical trial and will be further explored as a pan-cancer imaging biomarker for FAP expression and as a stratification tool for FAP-targeted therapies." (PMID 37046676, 2023). "Furthermore, the expression of this protein could be detected by immunohistochemistry, making FAP a good potential prognostic marker in RCC and several other cancers." (PMID 37175653, 2023). "Notably, the FAP-targeted probes, [68Ga]Ga-DOTA-FAPI-04 and [68Ga]Ga-DOTA-FAPI-46, were introduced as suitable radioligands for imaging different cancers and demonstrated high tumor uptake and fast clearance from the normal tissue, resulting high image quality." (PMID 37277339, 2023). "Consequently, specific traits of CXCR4 and FAP cannot be exclusively attributed either to cancer cells or non-malignant immune cells or fibroblasts." (PMID 36672341, 2023). "Furthermore, we performed in vitro cell staining, which showed induced ITGA5 and FAP expression levels in activated HMFs compared to non-activated HMF or cancer cells." (PMID 36831470, 2023). "However, targeting FAP+ cells can be non-selective towards cancer due to the wide expression of FAP in different cells." (PMID 35814453, 2022). "Radiolabeled FAP-targeting small ligands based on FAP inhibitors (FAPI) have recently been introduced and demonstrated very promising characteristics for PET imaging such as high and fast uptake in a variety of cancers and rapid clearance from the majority of healthy organs." (PMID 34957527, 2022). "FAP expression was moderate in a concurrently resected benign elastofibroma dorsi (patient 3) and was moderate to strong in 2 areas of radial scarring and biopsy site changes in benign breast tissue without cancer (patient 11)." (PMID 34740953, 2022). "In addition, FAP is almost exclusively expressed in chronic inflammation, wound healing, and cancer, thus absent from healthy tissues." (PMID 35788730, 2022).